VIM (vimentin)
Diseases named in the same sentence as VIM in open-access papers (continued):
Sharing a sentence is not in itself a finding about the gene and the disease.
tumor (continued). "Using immunohistochemistry, the present PSC case was confirmed with the positive staining of epithelial markers (CK and EMA) and a mesenchymal marker (Vimentin), while Ki67 positivity confirmed the aggressiveness of PSC in tumor cell proliferation." (PMID 31500651, 2019). "To illustrate the anti-metastatic mechanism of YFTL, we measured E-cadherin, N-cadherin, Vimentin, MMP-2, and MMP-9 expression in tumor and lung tissues of Lewis lung cancer mice by immunohistochemistry and Western blot analysis." (PMID 30781674, 2019). "IHC analysis of liver orthotopic xenograft tumor of nude mice revealed that RNF187, Vimentin, and Snail expression levels were higher in tumors derived from HCCLM6-shcontrol cells than in tumors derived from HCCLM6-shNotch1." (PMID 31477177, 2019). "Immunohistochemical staining showed a Ki67 index of 8% in the tumour cells, strong and diffuse positivity for CD34 and STAT6, and zonal positivity for vimentin and CD99." (PMID 31228959, 2019). "Vimentin is a type III IF protein abundant in cells having mesenchymal origin as well as cultured and tumor cells." (PMID 30627484, 2019). "We observed higher expression of E‐cadherin and lower expression of vimentin in xenografts derived from sh‐KK‐LC‐1 HCCLM3 cells, and lower E‐cadherin and higher vimentin in tumours originating from KK‐LC‐1‐OE Huh7 cells." (PMID 30895661, 2019). "To rule out the effect of cell culture, we additionally assessed the expression of SOX2, Vimentin and CD44 protein in NF1-LRD-expressing tumor." (PMID 30967630, 2019). "miR-142-3p functions in a tumor suppressive role in the invasion and EMT of CC cells through inhibition of the Frizzled 7 receptor (FZD7), vimentin, and Snail with up-regulation of E-cadherin." (PMID 30833362, 2019). "Immunohistochemically, the tumor cells were diffuse moderately or strongly positive for CD10, P504S, vimentin, PAX8, RCC, AE1/AE3, and SDHB and focally positive for CK7 and CA IX while negative for cathepsin K, HMB45, Melan-A, Ksp-cadherin, and CD117." (PMID 31828108, 2019). "Correlation analysis of the tumor stage and expressions of HER2, E‐cadherin, and Vimentin indicated that regulation of HER2 expression is related with EMT phenotypes of and tumor progression." (PMID 30714677, 2019). "We stained the subcutaneous tumor sections with antibodies against E-cad, an epithelial marker, as well as ZEB1, vimentin and fibronectin, which are mesenchymal markers." (PMID 31331982, 2019). "To do this, we analyzed the expression of epithelial (E-cadherin; ECAD) and mesenchymal (Vimentin; VIM) characteristics in tumor tissues obtained from treatment naive and matched locally-recurrent samples from the patients with oral SCC (OSCC; n = 20)." (PMID 30467425, 2018). "More attention has been paid to the roles of PHF8 in promoting tumor metastasis and EMT by co-transcriptionally activating SNAI1 and VIM expression, which was consistent with the current results." (PMID 30180906, 2018). "The TMA with combined primary tumour and metastasis tissue was tested for Connexin, Tks5, MAD, TWIST, vimentin, PLCγ, and CXCR4." (PMID 29976164, 2018). "Of the 45 patients, 27 tumor samples resembled an EMT-like phenotype, as assessed by high vimentin and low E-cadherin levels." (PMID 29596469, 2018). "miR-876-5p, which functions as a tumor suppressor in HNSCC, inhibits metastasis by targeting vimentin and provides a novel therapeutic target for HNSCC treatment." (PMID 30181714, 2018). "In the mouse xenograft models, the mRNA level of ZEB2, vimentin and N-cadherin was downregulated while E-cadherin was up-regulated in the DLX6-AS1 knock-down group with reduced tumor size and suppressed tumor metastasis." (PMID 30250401, 2018). "The me_HR-transformed MSCs possessed the original mesenchymal marker, vimentin, but started expressing the commonly observed stem cell marker CD133 in the tumor mass that developed." (PMID 30249017, 2018).
tumor (continued). "Original tumor, R2J, cultured in monolayer (2D) and in spheres showed a persistence expression of CD44, CD56 (except in monolayer), EGFR, Ki67, Nestin, and vimentin." (PMID 30583471, 2018). "We found that tumor cells treated with PF562271 or LY294002 expressed high levels of E-cadherin and low levels of N-cadherin, vimentin, snail and slug compared with control cells." (PMID 29426357, 2018). "Both tumor and PDPC models displayed epithelial (ECAD+/VIM−) cells in primary tumor and gain-of mesenchymal (ECAD+/VIM+) properties in metastatic state." (PMID 30467425, 2018). "Vimentin is a fragment of intermediate filament, and it is also an EMT marker mediating migration of tumor cells." (PMID 29899164, 2018). "Compared to the original tumor, R2J cells in culture (2D and spheres) lost the GFAP and CD56 expressions (only 2D) whereas Ki67, vimentin and nestin expressions were conserved as well as mesenchymal shift markers, such as CD44." (PMID 30583471, 2018). "The cells express epithelial (pan‐cytokeratin) and mesenchymal (vimentin) characteristics, CA125 and p16, like the original tumor." (PMID 30109783, 2018). "At the new tumour site de-repressed E-cadherin facilitates cell adhesion, and then inhibition of ZEB2, leads to reduced Vimentin and lowered invasive capabilities resulting in a stable secondary tumour." (PMID 29963231, 2018). "As compared to CD133− tumor cells, CD133+ ICC lost epithelial marker E-Cadherin and acquired mesenchymal marker Vimentin, indicating an EMT-like alteration in these tumor cells." (PMID 29510695, 2018). "Pure double-positive cells (keratin+/vimentin+) were also recovered from four FFPE samples to analyze cells excluding stromal cells and tumor cells in FFPE sample." (PMID 29525983, 2018). "When compared ex vivo tumor cells with parental cells, hallmarks of EMT including E-cadherin, Vimentin, Snail, and ZO-1 were altered significantly." (PMID 29507684, 2018). "Consistent with the previous in vitro experimental results, the expression of the epithelial marker E-cadherin was decreased in siRab27a/MHCC97H tumour tissues, accompanied by increased levels of the mesenchymal markers N-cadherin, α-SMA and vimentin." (PMID 29725020, 2018). "It is noteworthy that resveratrol strongly suppressed TNF-β-induced activation of tumor-promoting factors (NF-κB, MMP-9, CXCR4) and epithelial-to-mesenchymal-transition-factors (increased vimentin and slug, decreased E-cadherin) in CRC cells." (PMID 30002278, 2018). "Molecular analysis of the tumor tissues showed that melatonin decreased the levels of p-Akt, p-ERK, cyclin D1, PCNA, Bcl-2, Vimentin, Snail, HIF-1α, and VEGF, but upregulated the expressions of Bax and E-cadherin." (PMID 29725496, 2018). "Factors such as VIM, ITGß1-BP1 and MAP2K were also increased in expression in the distal region of stroma from tumor and can contribute to tumor dormancy." (PMID 30325954, 2018). "TGFβ can also act on Snail, Slug and other transcription factors via the RhoA/Cdc42, JKN/p38, Erk1/2 and PI3K/Akt pathways to downregulate E-cadherin expression and upregulate vimentin expression and mediate EMT in tumor cells." (PMID 30157906, 2018). "It is important to note that overexpression of vimentin has been used for decades as a clinical marker for EMT, a critical process in tumour cell dissemination." (PMID 30248895, 2018). "Once in the tumor microenvironment, MSC acquire expression of TAF antigens, such as a-smooth muscle actin (a-SMA), fibroblast-specific protein, vimentin, and SDF-1 in vivo and in vitro following co-culture with tumor cells or using tumor-conditioned media." (PMID 30526687, 2018). "High HIF1α expression leads to increased proliferation and invasion of tumour cells as well as inducing expression of genes involved in EMT, such as vimentin, VEGF and E-cadherin." (PMID 29844410, 2018). "In our case, immunohistochemistry revealed that the tumor cells expressed cytokeratin, NSE, and vimentin." (PMID 27166275, 2018).
tumor (continued). "Among these lncRNAs, GAS5 was recently reported to be a tumor suppressor lncRNA because it has been shown to inhibit HCC proliferation and EMT progression by inhibiting the expression of genes such as vimentin." (PMID 29382035, 2018). "Tumor cells undergoing EMT differentiate into a mesenchymal state, often indicated by molecular markers such as vimentin, desmin and α-smooth muscle actin (α-SMA)." (PMID 29562695, 2018). "Like the original tumor, NUCOLL43 expressed both epithelial (pan‐cytokeratin) and mesenchymal (vimentin) characteristics." (PMID 30109783, 2018). "RT-qPCR analysis of tumor revealed that doxorubicin induced ACTA2, VIM and SOX2 whereas addition of T12 reduced SOX2 expression." (PMID 29541394, 2018). "Immunostaining analysis revealed massive accumulation and invasion of vimentin-positive MSCs and CD3+ T cells at largely coinciding areas in the tumor tissues of Sipa1−/− mice, whereas these host cells were scarce in the tumor tissues of Wt mice." (PMID 29500416, 2018). "Based on the immunohistochemical staining results, compared with the untreated doxycycline groups, E-cadherin and α-SMA exhibited high expression levels, whereas vimentin, MMP2 and MMP9 exhibited low expression in tumor tissue." (PMID 28187433, 2017). "Not only can cripto-1 induce EMT properties in vitro, but Mouse Mammary Tumour Virus (MMTV)-Cripto transgenic mice form tumours that display EMT features including the downregulation of E-cadherin and the upregulation of vimentin and N-cadherin." (PMID 29108289, 2017). "As presurgery tumor markers, E-cadherin was correlated with both serum CEA (P = 0.007) and CA19-9 (P = 0.048) and vimentin was correlated with serum CA19-9 (P = 0.009)." (PMID 28744307, 2017). "The mean difference of vimentin and DAPK1 serum levels between tumour area groups was statistically insignificant (p = 0.072)." (PMID 28616237, 2017). "When co-cultured with A549 or primary NSCLC tumor cells, tumor-derived myeloid cells induced an EMT phenotype, with increased levels of the mesenchymal markers N-cadherin and vimentin, as well as augmented invasive activities." (PMID 28686632, 2017). "Compared to its original tumor, an elevated level of EMT markers, N-cadherin and Vimentin, was found in Ymac-1." (PMID 28596515, 2017). "Conversely, xenografted tumor tissues from the shPPA1-2 group expressing low levels of PPA1 exhibited a strong E-cadherin and weak Vimentin expression profile." (PMID 29100310, 2017). "After resection, the tumor’s histology and immunohistochemistry (positive for CD99, vimentin and synaptophysin) results suggested ES/PNET." (PMID 28472972, 2017). "VIM, TWIST1, AKT2, and SNAI1 are expressed in CRC pathological tissues, where they promote tumor metastasis by inducing the EMT process." (PMID 28030836, 2017). "The 2HF treated tumor tissues also showed a decrease in anti-apoptotic protein BCL-2 and mesenchymal markers vimentin and fibronectin." (PMID 29088842, 2017). "Carcinoma cells expressing markers of mesenchymal cells, such as vimentin, α-SMA, FSP1 and desmin, are frequently seen at the invasive fronts of tumours." (PMID 28430163, 2017). "At immunohistochemistry, the tumor cells were diffusely positive for S-100 protein, pan-keratins, EMA, and vimentin." (PMID 28409046, 2017). "We also analyzed the levels of vimentin and matrix metalloproteinase-2 (MMP-2), levels of which are known to increase in EMT-undergoing cells and promote tumor invasion." (PMID 28193222, 2017). "Immunohistochemistry analysis was conducted to assess the protein abundance of DACH1, CD44, Myc, Sox2, Fibronectin, Vimentin, EGFR, Ki-67 in nude mice xenograft tumor tissues with overexpression of DACH1 and the GFP controls." (PMID 28659634, 2017). "Immunohistochemical staining for E-cadherin, Occludin, Vimentin, and N-cadherin showed that PTL increased E-cadherin and Occludin levels, whereas it decreased Vimentin and N-cadherin levels in tumor tissues." (PMID 29050271, 2017).
tumor (continued). "This tumor expressed higher levels of both phospho-AXL and SMO when treated with osimertinib, concomitantly with increased levels of vimentin and PDL-1." (PMID 28416737, 2017). "Hif-2α was positively correlated with the expression of vimentin, Ki-67, CD31, and negatively correlated with the expression of E-cadherin, indicating that hif-2α facilitated EMT and promoted tumor growth in the mouse model." (PMID 28705232, 2017). "When compared to the primary tumor, the expression of some EMT markers, CDH11 and vimentin, is elevated in CTCs, whereas others, S100A4, Itga5, Sdc1, are decreased." (PMID 28544498, 2017). "These tumours expressed the AML marker proteins HMB45, SMA, VIMENTIN, PDGFRβ and epithelial structures were positive for E-CADHERIN." (PMID 29133867, 2017). "Mesenchymal markers, including FN1 and vimentin (VIM), were overexpressed in tumor buds compared with IEC and CCPT, thus suggesting an EMT phenotype that was characteristic of the tumor bud cells." (PMID 28687755, 2017). "Since E-Cadherin, N-Cadherin, Vimentin, and ZEB1 were considered as potential vital genes implying higher malignancy of tumor cells; Western blot analysis was performed to detect the protein level alteration." (PMID 28903320, 2017). "Clusters of CD8+ T lymphocytes were observed at the periphery of small residual tumor masses in the peritoneal cavity, which presented a significant reduction in mitotic index, IL6 and vimentin expression compared with tumors in untreated rats." (PMID 28915695, 2017). "FBLN1 and VIM methylation was also studied in liver tissues (including HCC tissue and paired adjacent non-tumor tissue) from separate nine cases from the French case series." (PMID 28333958, 2017). "We found that the expression levels of fibronectin, vimentin, N-cadherin, and SNAIL were decreased, but the expression of E-cadherin was increased in the Bmi-1- depleted tumor cells." (PMID 28424413, 2017). "In our immunohistochemical analyses, the tumor levels of pro-differentiation marker E-cadherin was increased by 2HF exposure, which was paralleled by a decrease in EMT markers vimentin and fibronectin." (PMID 29088842, 2017). "The weak expression of E-cadherin and strong expression of vimentin are traditional markers of EMT and these expression patterns are currently used to identify cells that have undergone EMT in circulating tumor cells." (PMID 28786996, 2017). "Here, we show that pharmacological inhibition of LSD1 inhibits the aggressive features of OSCC by inhibiting key target genes that function in the tumor microenvironment and EMT, including CCN2/CTGF, MMP13, LOXL4 and vimentin." (PMID 29088714, 2017). "To gain additional mechanistic insight into the role of MRPS23 in the metastasis cascade, we focus on the epithelial marker E-cadherin and mesenchymal marker vimentin, which play a major role in the EMT process that contributes to tumour progression." (PMID 29069745, 2017). "In short, these results suggest that the tumor suppressor role of miR-320a in GC cells is mediated or at least partially mediated by the downregulation of USP14 and vimentin expression." (PMID 27448976, 2017). "Western blot analysis of E-cadherin, vimentin, and HMGA2 expression confirmed the tumor aggressiveness of CL1-5 cells." (PMID 29079814, 2017). "Instead, the tumour cells were themselves mesenchymal‐like and expressed the typical mesenchymal genes ZEB2 and VIM, indicating a tumour type that has undergone epithelial–mesenchymal transition (EMT)." (PMID 28195647, 2017). "This up-regulation expands to other potential tumor markers including A1AT1, tropomyosin-4, TUBB3, ACTN4, DDX3X, LMNB1, PARP and vimentin." (PMID 29109428, 2017).
tumor (continued). "Consistent with the in vitro experiments results, knockdown of FMNL3 in vivo also led to up-regulation of E-cadherin and down-regulation of Vimentin and MMP-9 in tumour cells in xenographs." (PMID 28198387, 2017). "Histologically, the tumours stained negatively for CD31, DESMIN, MYOD1, MYOGENIN, alpha-SMA and positively for VIMENTIN." (PMID 28982163, 2017). "Vimentin and CD34 are related to tumor growth, invasion, and metastasis; however, Ki67 protein is a marker of tumor cell proliferation." (PMID 28358024, 2017). "To further validate the molecular basis, we then performed immunohischemistry on the tumor xenografts to detect the level of proliferation marker Ki67, EMT-related vimentin, apoptosis-related caspase 3 and the Akt signaling inhibitor PTEN in vivo." (PMID 28126034, 2017). "The basal/SCC‐like tumour samples also expressed ZEB2 and VIM, but only in surrounding stromal cells." (PMID 28195647, 2017). "In this regard, expression of BANCR is reduced in patient tumours, and re-expression of BANCR levels induced E-cadherin expression, along with decreased N-cadherin, Vimentin, SNAIL1, and SNAIL2 expression." (PMID 28430163, 2017). "EMT is a crucial step during tumor cell migration and invasion; ZEB1, E-cadherin and Vimentin have been widely used as classic EMT markers." (PMID 28489585, 2017). "IHC staining of miR-3656 tumor sections confirmed reduced RHOF, increased epithelial marker E-cadherin and reduced expression of the mesenchymal markers TWIST1 and Vimentin." (PMID 29048402, 2017). "Immunohistochemically, the tumor cells were strongly positive for CK7, EMA, vimentin, SOX10, S-100, and focally positive for CA9." (PMID 29041930, 2017). "Routine IHC analysis of this tumor showed positive staining of endothelial markers CD31, CD34, smooth muscle marker Calponin, and mesenchymal cell marker vimentin." (PMID 29113426, 2017). "It is worth noting that we identified the trace of tumor cells expressed PCK and Vimentin in lymph nodes of all G3 CNB samples (d: patient ID36)." (PMID 29259164, 2017). "Oleate-induced PTX3 enhanced the expression of vimentin and matrix metalloproteinase-3 (MMP-3) to regulate tumor invasion." (PMID 28489600, 2017). "Similar effects were also observed in vivo on tumor xenografts, wherein PAC increased the expression of E-cadherin and repressed N-cadherin, vimentin, AKT and Twist1." (PMID 27465411, 2016). "Tumour cells in both: breast and pulmonary lesions were positive for cytokeratin and EMA (epithelial cells) and also for SMA, S100 and vimentin (myoepithelial cells)." (PMID 27487934, 2016). "The xenograft tumor samples were then analyzed by IHC for levels of proteins such as HIF-1α, E-cd, Claudin-4, and VIM." (PMID 27806701, 2016). "The tumor cells reacted with immunohistochemical stains for desmin, smooth muscle actin, SMMHC, CD34 (focal), and vimentin." (PMID 27747117, 2016). "Several studies have reported the individual expression pattern and function of each hub (TK1, CSNK2B, VIM, YWHAB and HSP90AB1) in different tumors and tumor models in vitro." (PMID 27527857, 2016). "Intriguingly, almost no changes in the expression of vimentin (VIM, which acts as one of major mesenchymal markers) were observed, but this was instead accompanied by modestly increased abundance of the epithelial marker E-cadherin-associated α-catenin, in Nrf1α−/−-derived xenograft tumours." (PMID 27065079, 2016). "Immunohistochemical evaluation showed that the tumor cells were positive for cytokeratin AE1/AE3, CAM5.2, vimentin, prostate specific acid phosphatase, and androgen receptor and negative for PSA, S-100, CD34, CD68, and smooth muscle actin." (PMID 27843661, 2016). "Firstly, we respectively analyzed the correlation of expression levels of TUSC7 and E-cadherin as well as TUSC7 and vimentin in 75 paired HCC tissues and adjacent non-tumor tissues by immunohistochemical staining." (PMID 27002617, 2016).